DNMT3L (DNA methyltransferase 3 like)
Diseases named in the same sentence as DNMT3L in open-access papers (continued):
Sharing a sentence is not in itself a finding about the gene and the disease.
cancer (20 papers, 2008 to 2025). A tumor composed of atypical neoplastic, often pleomorphic cells that invade other tissues. "ARPC2 expression was more closely related to DNMT1, which showed a positive correlation in 19 types of cancer and an inverse correlation in four cancer types, but was less closely associated with DNMT3L." (PMID 35733852, 2022). "Previously, we had identified a CpG island within the human DNMT3L promoter and first exon that showed loss of DNA methylation in cancer samples." (PMID 24743422, 2014). "There is a possibility that the loss of methylation at DNMT3L DMC observed in cancer samples was merely a reflection of nuclear reprogramming observed in cancer." (PMID 24743422, 2014). "Finally, the importance of identifying a cis-regulatory element (a PRE) with in the DNMT3L gene should be viewed in light of the loss of DNA methylation at the DNMT3L DMC observed in certain cancers." (PMID 24743422, 2014). "The available data regarding DNMT3L mRNA and protein expression in different cancer subtypes are very limited." (PMID 37894317, 2023). "Our study found that RMI2 is related to DNA methylation in multiple types of cancer, among which BRCA, STAD, UCEC is associated with four DNA methylation genes (DNMT3L, DNMT3B, DNMT3A, DNMT1)." (PMID 35552266, 2022). "As this region showed differential DNA methylation profiles in normal and cancer samples we have referred to it as DNMT3L DMC (Diffferentially Methylated in Cancer) in this manuscript." (PMID 24743422, 2014). "A regulator of de novo DNMTs, DNMT3a and DNMT3b, DNMT3L promoter was found to have lost DNA methylation to varying levels in 14 out of 15 cancer cervix samples that were analyzed." (PMID 24822169, 2014). "However, research on DNMT3L in cancer is very limited, and its role and mechanism are still largely unclear." (PMID 38308276, 2024). "DNMT3L is a novel marker and is essential for the growth of human carcinoma." (PMID 35903675, 2022). "However, further work would be required to identify the regulatory framework for DNMT3L in cancer patients and establish the role of this regulatory element during carcinogenesis." (PMID 24743422, 2014). "DNMT2 or TRDMT1 and DNMT3L are yet to be studied in detail in the different cancers." (PMID 24822169, 2014). "Additional studies are required for the precise role for DNMT3L on other cancers." (PMID 24822169, 2014). "Variants in other DNMTs (i.e. DNMT3L, DNMT1) have been associated with human cancers." (PMID 21347319, 2011). "Consequently, we postulated that DNMT3L might exert its anti-cancer function by inhibiting DNA methylation." (PMID 38308276, 2024). "Additionally, CDO1 was identified as a target gene of DNMT3L and also exhibits anti-cancer effects." (PMID 38308276, 2024). "However, it is widely known that the levels of DNMTs, (DNMT3B, DNMT3A, and DNMT3L) are often increased in various cancer tissues and cell lines, and may account for the hypermethylation of tumor suppressor genes in a variety of malignancies." (PMID 34063128, 2021). "In our previous study, we had identified a CpG island spanning the promoter (DNMT3L-002, Ensembl Transcript ID ENST00000431166) and Exon 1 (DNMT3L-001, Ensembl Transcript ID ENST00000270172) of the human DNMT3L gene that showed loss of DNA methylation in different cancers." (PMID 24743422, 2014). "The levels of DNMTs, especially those of DNMT3B, DNMT3A, and DNMT3L, are often increased in various cancer tissues and cell lines, which may partially account for the hypermethylation of promoter CpG-rich regions of tumor suppressor genes in a variety of malignancies." (PMID 24822169, 2014).
cancer (continued). "Given that DNMT3L can inhibit methylation and promote expression of CDO1, we hypothesized that its anti-cancer role might be mediated through CDO1." (PMID 38308276, 2024). "Additionally, we explored the correlation between IL18RAP and five methyltransferases (DNMT3L, DNMT3B, DNMT3A, TRDMT1, and DNMT1) across cancers." (PMID 37698530, 2023). "Ιn our study, we observed an overexpression of the DNMT3L protein in high-grade carcinomas compared to low-grade tumors and non-neoplastic epithelium and in relapses compared to primary neoplasms." (PMID 37894317, 2023). "In addition, our transcriptomic data did not link the ectopic expression of Dnmt3l to cancer-related outcomes." (PMID 32195249, 2020). "Similarly, the DNMT1, DNMT3A and DNMT3L protein levels were overexpressed and DNMT2 expression was reduced in high-grade carcinomas compared to non-neoplastic tissue and low-grade tumors." (PMID 37894317, 2023).
tumor (9 papers, 2011 to 2024). "On the other hand, DNMT3L association with 3 of the 5 down regulated genes promoters was distinctly increased in the tumor bearing G5 larvae as compared to the other generations." (PMID 26795243, 2016). "Furthermore, DNMT3L was associated with inhibition signals of tumor metastasis, invasion, and proliferation." (PMID 38308276, 2024). "Based on our previous data analysis and experimental validation, we have confirmed the anti-tumor function of DNMT3L and CDO1, and have demonstrated that DNMT3L can regulate both the DNA methylation and expression of CDO1." (PMID 38308276, 2024). "Out of these datasets, 20 contained both HCC and non-tumor samples, along with corresponding DNMT3L expression values." (PMID 38308276, 2024). "DNMT3A is overexpressed in the early stages only, whereas DNMT1 and DNMT3L are also overexpressed in tumor relapses." (PMID 37894317, 2023). "Repressive chromatin marks H3K9me3 and H3K27me3 were unaffected due to DNMT3L expression but the levels of the active histone marks H3K4me3, H3K4me2 and H3k36me3 were dramatically reduced in tumor bearing G5 3rd instar larvae." (PMID 26795243, 2016). "Namely, we hypothesize that DNMT1 and DNTM3A seem to play a role in tumor initiation, DNMT3B in tumor progression and DNMT3L in tumor relapse, whereas DNMT2 may have an opposite role." (PMID 37894317, 2023). "Moreover, through the integration of big data analysis and experimental validation, we have clarified the anti-tumor activity of CDO1 in HCC, and the rescue experiments have shown that DNMT3L can effectively suppress tumor growth and metastasis by regulating CDO1." (PMID 38308276, 2024). "Further functional experiments indicated that DNMT3L could inhibit cell cycle progression, proliferation, apoptosis resistance, invasion, and migration in vitro, as well as suppress tumor growth and metastasis in vivo, which is consistent with the findings of big data analysis." (PMID 38308276, 2024). "Considering our comprehensive analysis of DNMT expressions across the progression of OEC, we hypothesize that DNMT1 and DNTM3A seem to play a role in tumor initiation, DNMT3B in tumor progression and DNMT3L in tumor relapse, whereas DNMT2 may have an opposite role, acting as a tumor-suppressor gene." (PMID 37894317, 2023). "Conversely, when DNMT3L expression is abnormal, DNMT3A can facilitate the methylation of CDO1 promoter, thus downregulating CDO1 expression and promoting tumor growth and metastasis." (PMID 38308276, 2024). "The tumor formation assay in nude mice gave negative results, disproving a tumorigenic function for Dnmt3l in DNMT3L-treated MEFs (data not shown)." (PMID 32195249, 2020). "It is interesting to speculate that the observed hypomethylation of the DNMT3L promoter in normal gut mucosa in the HPS patients identified here, may also play a role in the aberrant de novo establishment of tumour suppressor methylation seen in most CRC." (PMID 21347319, 2011).
infection (3 papers, 2015 to 2016). The state of being infected such as from the introduction of a foreign agent such as serum, vaccine, antigenic substance or organism. "After infection we obtained polyclonal cell populations expressing a specific DNMT3B isoform or DNMT3L in DKO8 and 3BKO cells." (PMID 27121154, 2016). "Only DNMT3L displays differential expression upon HBV infection (statistically significant at 24 h post-infection)." (PMID 26565721, 2015). "At every 24 hours within 4 days after lentiviruses infection of SiHa and CaSki, we used Q-PCR to analyze the expression of E6, E7, DNA methyltransferase genes (DNMT1, DNMT3A, DNMT3B and DNMT3L), and tumor suppressor genes (MT1G, NMES1, RRAD, SFRP1, SPARC and TFPI2)." (PMID 26329329, 2015).
mental illness (1 paper, 2014). "DNMT3L rs2070565 CC genotype and C allele was found to be significantly higher in patients with family history of mental illness and who developed the disease at an earlier age compared to those who developed at normal or older age." (PMID 24859147, 2014).
DNMT3L also shares sentences with these, for which no sentence is quoted: thymoma (2 papers); alcoholic hepatitis (1); Angelman syndrome (1); breast carcinoma (1); Intellectual disability (1); lentivirus infection (1); leukemia (1); lung carcinoma (1); lung disease (1); metastatic tumors (1); neuroblastoma (1); pancreatic cancer (1); prostate carcinoma (1); serous carcinomas (1); teratoma (1); testicular germ cell tumor (1); testicular tumours (1).